CDHR1 (cadherin related family member 1)
Diseases named in the same sentence as CDHR1 in open-access papers:
CDHR1 is named in the same sentence as 36 diseases in open-access papers, as found by Europe PMC text mining. Sharing a sentence is not in itself a finding about the gene and the disease. The quoted sentences say what the papers report.
Retinal dystrophy (15 papers, 2011 to 2026). Retinal dystrophy is an abnormality of the retina associated with a hereditary process. "To date, more than 460 retinal dystrophy genes have been described in the literature, with CDHR1-associated retinopathies (OMIM *609502) accounting for less than 1% of these cases." (PMID 41595520, 2026). "Genetic variants in CDHR1 have been associated with a number of inherited retinal dystrophies including retinitis pigmentosa and cone-rod dystrophy." (PMID 36848389, 2023). "Ten patients from nine unrelated families with retinal dystrophy and CDHR1 variants were identified." (PMID 35627310, 2022). "The genomic structure of CDHR1 was first reported in 2005, and mutations in this gene cause retinal dystrophies." (PMID 35627310, 2022). "Similar clinical findings were observed in patients with autosomal recessive PROM1 retinal dystrophy and in patients who harbored a cis-acting recessive allele in CDHR1 along with the RGR mutation." (PMID 35627310, 2022). "Further studies are required to better understand correlation between genotype and phenotype in individuals with CDHR1-associated retinal dystrophies." (PMID 35627310, 2022). "Missense, nonsense, and copy-number variants in the CDHR1 gene have been reported to cause retinal dystrophy." (PMID 35627310, 2022). "A variant of CDHR1, another member of the cadherin superfamily that is specific to photoreceptors, was reportedly associated with inherited retinal dystrophies and is a possible target for further scrutiny." (PMID 36498929, 2022). "Over the past decade, additional studies have reported novel variants in CDHR1 and have demonstrated the correlation between phenotype and genotype in patients with CDHR1 retinal dystrophies." (PMID 35627310, 2022). "It is conceivable that the frameshift mutation of CDHR1 is the cause of retinal degeneration in these individuals because mutations in CDHR1 are associated with retinal dystrophies." (PMID 32493732, 2021). "While the relation between the levels of this protein and glaucoma is yet to be explored, mutations in CDHR1 have been associated with retinal dystrophies." (PMID 33808966, 2021). "Apart from the variants described in this study, 20 mutations in CDHR1 that explain the disease phenotype in the respective patients have been associated with retinal dystrophies to date." (PMID 28765526, 2017). "The retinal dystrophy phenotype associated with CDHR1 retinopathy is clinically heterogenous." (PMID 35627310, 2022). "The hypothesis posed by our study can be generalized to other early-onset, cone-dominated dystrophies associated with myopia, such as CDHR1 and RP2 retinal dystrophies." (PMID 40535564, 2025). "In this study, we describe the clinical and molecular findings of a retinal dystrophy cohort (10 patients) attributed to autosomal recessive CDHR1 and report novel variants in populations not previously identified with CDHR1-related retinopathy." (PMID 35627310, 2022). "In all eight cases, rare and potentially disease-causing variants compatible with a model of autosomal recessive inheritance were only observed in the CDHR1 gene, but not in other genes associated with retinal dystrophies." (PMID 28765526, 2017). "Cdhr1 was identified as one of three non-classical cadherin genes and was reported to be a candidate gene for retinal dystrophies." (PMID 26986842, 2016).
cone-rod dystrophy (13 papers, 2012 to 2026). Inherited retinal dystrophies that belong to the group of pigmentary retinopathies. "Mutations in CDHR1, a photoreceptor specific cadherin have been found to be associated with the incidence of cone-rod dystrophy and recapitulated in mouse CDHR1 knockouts." (PMID 41648145, 2026). "A well-established candidate gene associated with cone-rod dystrophy which has yet to be explored in a developmental context is photoreceptor specific cadherin CDHR1." (PMID 33330480, 2020). "We report ophthalmic and genetic findings in patients with autosomal recessive retinitis pigmentosa (RP), cone-rod dystrophy (CRD) or cone dystrophy (CD) harboring potential pathogenic variants in the CDHR1 gene." (PMID 28765526, 2017). "The phenotypes from our 13 patients demonstrate that mutations in the CDHR1 gene can lead both to retinitis pigmentosa (RP) and cone dystrophies (CD) or cone-rod dystrophies (CRD)." (PMID 28765526, 2017). "Here we report a novel splice site mutation of CDHR1, c.1485+2T>G, underlying autosomal recessive cone-rod dystrophy in a consanguineous Israeli Christian Arab family." (PMID 23233793, 2012). "Mutations in CDHR1, a retina specific cadherin, are associated with cone-rod dystrophy." (PMID 33330480, 2020). "A CDHR1 knockout mouse partially supports this hypothesis as well as the correlation of CDHR1 loss of function and cone-rod dystrophy." (PMID 33330480, 2020). "While the mechanism as to how loss of CDHR1 function affects pathogenesis of cone-rod dystrophies is unknown, several studies have reinforced its importance to photoreceptor cell biology by characterizing its protein localization and necessity for photoreceptor disk renewal." (PMID 33330480, 2020). "Clinically, CDHR1 variants are associated with cone dystrophies (COD), central areolar choroidal dystrophy (CACD), cone-rod dystrophies (CORD), rod-cone dystrophies (RCD), and late-onset macular dystrophy (LOMD)." (PMID 41595520, 2026). "CDHR1 (OMIM: #609502) is related to cone and rod dystrophy and autosomal recessive RP by contributing to the maintenance of the photoreceptor structure." (PMID 37895187, 2023). "Mutations in four cadherin, namely CDHR1, CDH23, PCDH15, CDH3, the latter being the dominant RPE cadherin, have been identified as causes of inherited retinal degeneration, including cone-rod dystrophy, macular dystrophy and Retinitis Pigmentosa." (PMID 36645183, 2023). "CDHR1, TTLL5, PRPF6, and IFT140 have been reported to play roles in human disorders of cone-rod dystrophy and cone dystrophy or retinitis pigmentosa." (PMID 35456484, 2022).
retinitis pigmentosa (8 papers, 2017 to 2024). Retinitis pigmentosa (RP) is an inherited retinal dystrophy leading to progressive loss of the photoreceptors and retinal pigment epithelium and resulting in blindness usually after several decades. "Until recently, the phenotypes associated with CDHR1 mutations were autosomal recessive cone–rod dystrophy and retinitis pigmentosa, both leading to severe visual impairment in adulthood." (PMID 32681094, 2021).
retinal degeneration (5 papers, 2010 to 2021). Degeneration of the retina. "The clinical findings of our four RP patients show that the rod-cone retinal degeneration caused by mutations in the CDHR1 gene is of the RP type with early macular involvement." (PMID 28765526, 2017). "CDHR1 was therefore an obvious candidate for human retinal degeneration." (PMID 23233793, 2012).
glioma (4 papers, 2021 to 2024). A benign or malignant brain and spinal cord tumor that arises from glial cells (astrocytes, oligodendrocytes, ependymal cells). "Second, the associations between expression levels of CDHR1 and glioma overall survival were tested using TCGA, CGGA, GSE4412 and GSE43378 datasets." (PMID 34335936, 2021). "All those results suggested that CDHR1 was associated with IDH mutation and MGMT methylation, and CDHR1 was an important prognostic factor of glioma." (PMID 34335936, 2021). "Moreover, the down-regulation of CDHR1 was associated with poor clinical outcomes of glioma in all TCGA, CGGA, GSE4412 and GSE43378 datasets." (PMID 34335936, 2021). "We showed that, CDHR1 was down-regulated in GBM and CDHR1 was down-regulated in IDH mutant glioma patients." (PMID 34335936, 2021). "Here, using TCGA, CGGA and Gene Expression Omnibus (GEO) datasets, we studied the differentially expressed genes between GBM and LGG, and our data suggested that low expression of CDHR1 was an independent unfavorable prognostic factor in glioma." (PMID 34335936, 2021). "Glioma patients with higher expression of CDHR1 had longer overall survival than glioma patients with lower expression of CDHR1 in all TCGA, CGGA, GSE4412 and GSE43378 datasets." (PMID 34335936, 2021). "We found that glioma patients with CDHR1 low EMP3 high expression had worse clinical outcomes in TCGA and CGGA datasets." (PMID 34335936, 2021). "We found that, consistent with the down-regulation of CDHR1 in GBM, the low expression of CDHR1 was a bad prognosis in glioma." (PMID 34335936, 2021). "Compared with normal brain tissues, the expression levels of CDHR1 were significantly down-regulated in glioma tissues in all TCGA, GSE44971 and GSE68848 datasets." (PMID 34335936, 2021). "All those results suggested that low expression of CDHR1 was an independent unfavorable prognostic factor in glioma." (PMID 34335936, 2021). "Moreover, most studies of CDHR1 in the brain have been related to gliomas, where downregulation of the protein is an unfavorable prognostic factor, and its overexpression prevents glioma growth and invasion." (PMID 38656449, 2024). "We then studied the different expression levels of CDHR1 in glioma patients with or without IDH mutations." (PMID 34335936, 2021). "Glioma patients with low CDHR1 and high EMP3 expression had worse clinical outcomes." (PMID 34335936, 2021). "First, the expression levels of CDHR1 in normal brain tissues and glioma tissues were tested." (PMID 34335936, 2021). "And low expression of CDHR1 was an unfavorable prognostic factor in glioma." (PMID 34335936, 2021). "At last, we determined the biological functions of CDHR1 in glioma." (PMID 34335936, 2021). "At last, we confirmed the function of CDHR1 by over-expression CDHR1 in glioma cell lines." (PMID 34335936, 2021). "Furthermore, over-expression of CDHR1 inhibited glioma cell invasion as tested using trans-well assay." (PMID 34335936, 2021). "Low expression of CDHR1 was an independent unfavorable prognostic factor in glioma." (PMID 34335936, 2021). "The prognostic effects of CDHR1 were further tested in glioma GBM subtype." (PMID 34335936, 2021). "So, the expression and prognostic effects of CDHR1 in glioma were further studied." (PMID 34335936, 2021). "The biological functions of CDHR1 in glioma were tested using CCK-8 and trans-well assays." (PMID 34335936, 2021). "While, glioma patients with CDHR1 high EMP3 low expression had better clinical outcomes." (PMID 34335936, 2021). "The prognostic effects of CDHR1 were also tested in glioma LGG subtype." (PMID 34335936, 2021). "Compared with normal brain tissues, CDHR1 was down-regulated in glioma tissues." (PMID 34335936, 2021). "Two glioma cell lines A172 and U87 were transfected with CDHR1 over-expression plasmid." (PMID 34335936, 2021). "At last, we showed that over-expression of CDHR1 could inhibit glioma cell growth and invasion." (PMID 34335936, 2021).
glioma (continued). "The over-expression of CDHR1 could significantly inhibit glioma cell growth and cell invasion." (PMID 34335936, 2021). "Indeed, CDHR1 was down-regulated in glioma tissues, compared with normal brain tissues." (PMID 34335936, 2021). "We speculated that, like other nine genes, CDHR1 was a potential prognostic marker in glioma." (PMID 34335936, 2021). "Many of them, such as CDHR1, DLL1, DLL3 and SCG3, have been reported to be potential therapeutic targets for glioma treatment." (PMID 35456975, 2022). "Moreover, the expression and prognostic significance of CDHR1 in glioma are never reported." (PMID 34335936, 2021).
retinal disease (4 papers, 2010 to 2026). "Compound heterozygosity could not be demonstrated for patient F and we have to point out that her phenotype might not be CDHR1-related, although no putative disease-causing variants in other retinal disease genes were identified in the panel sequencing approach." (PMID 28765526, 2017).
Macular dystrophy (3 papers, 2021 to 2023). Macular dystrophy is a nonspecific term for retinal degeneration, generally confined to the macula, usually presumed of genetic origin. "Heterozygous individuals in ABCA4 disease and control cohort harboring variants with MAF<0.005 and CADD score >25, in each macular dystrophy gene CDHR1, CHM, CRX, ELOVL4, PROM1, PRPH2, and ROM1." (PMID 35353811, 2022). "Heterozygous individuals in ABCA4 disease and control cohort harboring rare variants in macular dystrophy genes CDHR1, CHM, CRX, ELOVL4, PROM1, PRPH2, ROM1." (PMID 35353811, 2022). "The clinical records of patients with macular dystrophy and biallelic variants in CDHR1 were reviewed." (PMID 32681094, 2021).
psoriasis (3 papers, 2010 to 2017). An autoimmune condition characterized by red, well-delineated plaques with silvery scales that are usually on the extensor surfaces and scalp. "Notably, some genes strongly decreased in psoriasis lesions were elevated by IMQ in most strains (Syt8, Cdhr1, Cntn2)." (PMID 28279190, 2017).
central areolar choroidal dystrophy (2 papers, 2022 to 2026). "Patients with different truncating CDHR1 mutations showed diverse visual symptoms, including glare, reading difficulties, metamorphopsia, and reduced visual acuity, resembling central areolar choroidal dystrophy." (PMID 35656327, 2022).
prostate carcinoma (2 papers, 2016 to 2017). A carcinoma that arises from epithelial cells of the prostate gland. "CDHR1 and PAQR5 were the most significantly differential transcripts in prostate cancer and pancreatic cancer patients, respectively." (PMID 26786760, 2016).
astrocytoma (1 paper, 2021). "In TCGA and CGGA datasets, we showed that, compared with oligoastricytoma and oligodendroglioma, CDHR1 was down-regulated in astrocytoma subtype of LGG." (PMID 34335936, 2021). "Moreover, in GSE16011 dataset, the expression of CDHR1 was also lower in astrocytoma LGG subtype, compared with oligodendroglioma LGG subtype." (PMID 34335936, 2021). "Furthermore, CDHR1 was down-regulated in astrocytoma LGG subtype and low expression of CDHR1 was a bad prognosis of LGG." (PMID 34335936, 2021).
brain injury (1 paper, 2024). Acute and chronic (see also brain INJURIES, CHRONIC) injuries to the brain, including the cerebral hemispheres, CEREBELLUM, and brain STEM. "Cadherin-related family member 1 as a potential risk factor for traumatic brain injury." (PMID 38656449, 2024).
central serous chorioretinopathy (1 paper, 2021). "This feature could be part of the spectrum of CDHR1 maculopathy, but as it is detected in one patient, it could result from a process similar to central serous chorioretinopathy." (PMID 32681094, 2021).
ciliopathy (1 paper, 2018). A genetic disorder of the cellular cilia or the cilia anchoring structures, the basal bodies, or of ciliary function. "So far, such extra-ocular symptoms have not been described as a feature of CDHR1-related disease but would be typical features of a ciliopathy to which CDHR1-associated IRD does not belong to." (PMID 30576320, 2018).
glioblastoma (1 paper, 2023). The most malignant astrocytic tumor (WHO grade IV). "Cadherin-related family member 1 (CDHR1), a calcium-dependent cell-cell adhesion membrane protein, has prognostic significance in glioblastoma (GBM), with decreased CDHR1 expression being associated with poor clinical outcomes." (PMID 38327905, 2023).
melanoma (1 paper, 2021). A malignant, usually aggressive tumor composed of atypical, neoplastic melanocytes. "The expression levels of LTBP4 and CDHR1 in melanoma tissues were notably lower than those in the control group, while MARCKSL1 expression in melanoma tissues was notably higher than that in the control group." (PMID 35252214, 2021). "Next, the diagnostic ability of these three biomarkers in discriminating melanoma from the control samples demonstrated favorable diagnostic value, with the AUC values of 0.985 (95% CI 0.951–1.000) in LTB4, 0.949 (95% CI 0.839–1.000) in CDHR1, and 0.911 (95% CI 0.720–1.000) in MARCKSL1." (PMID 35252214, 2021).
retinopathy (5 papers, 2015 to 2026). "The natural history of CDHR1-associated retinopathy typically follows a slow progression, providing a therapeutic window, which makes the disease a candidate for gene therapy." (PMID 41595520, 2026). "In summary, we have identified new genotypes for predominantly macular disease in CDHR1-associated retinopathy." (PMID 32681094, 2021). "We identify the need for larger studies, likely multicenter, that hopefully will draw from diverse populations to better understand molecular aspects that correlate with the phenotype in CDHR1 retinopathy." (PMID 35627310, 2022). "The spectrum of CDHR1 retinopathy includes photoreceptor degenerations, CRD, and RCD." (PMID 35627310, 2022). "LOMD could be characterized as a milder spectrum-extending finding within the CDHR1 retinopathy presentation." (PMID 35627310, 2022). "Clinically, the diagnosis of these patients is consistent with a form of CDHR1-related retinopathy." (PMID 26350383, 2015). "Taken together, an early maculopathy might be a symptom to be expected in all patients with CDHR1-related retinopathy regardless of age." (PMID 28765526, 2017).
CDHR1 also shares sentences with these, for which no sentence is quoted: cone dystrophy (3 papers); autosomal recessive retinitis pigmentosa (2); myopia (2); Obesity (2); autosomal recessive cone rod dystrophy (1); basal cell carcinoma (1); colorectal cancer (1); gastric cancer (1); glaucoma (1); infection (1); keratoconus (1); Leber congenital amaurosis (1); macular degeneration (1); oligodendroglioma (1); pancreatic cancer (1); Photophobia (1); Renal insufficiency (1); secondary hyperparathyroidism (1); Usher syndrome type 1 (1).